IL13 (interleukin 13)
Diseases named in the same sentence as IL13 in open-access papers (continued):
Sharing a sentence is not in itself a finding about the gene and the disease.
glioma (continued). "For example, glioma-targeted therapy based on the delivery of chimeric protein comprising IL-13 and Pseudomonas exotoxin A (PE), has been already under development." (PMID 30718742, 2019). "We examined the activation of AP-1 family of transcription factors (c-Jun, Fra-1, Jun-D, c-Fos, and Jun-B) after treating U251, A172 (IL-13Rα2 +ve) and T98G (IL-13Rα2 −ve) glioma cell lines with IL-13 by RT-qPCR, and immunocytochemistry (ICC)." (PMID 30572904, 2018). "c-Jun and Fra-1 were only two transcription factors that were consistently induced by IL-13 in IL-13Rα2 positive glioma cell lines." (PMID 30572904, 2018). "C-Jun and Fra-1 transcription factors bound to nuclear fractions isolated from IL-13Rα2 positive IL-13 treated glioma cell lines (U251 and A172) compared to untreated cell lines at highly statistically significant level (P = 0.0018)." (PMID 30572904, 2018). "An in-depth investigation of the mechanism of interaction of the IL13 conjugated nanoliposomes with glioma tumors expressing IL13Rα2 and their ability to overcome the known drug resistance properties was described in our earlier study." (PMID 29304038, 2018). "Herein, we have investigated a role of IL-13/IL-13Rα2 axis in signaling through AP-1 transcription factors in human glioma samples in situ." (PMID 30572904, 2018). "Several studies have reported that SNPs in IL-4, IL-4R, and IL-13 were inversely correlated with the incidence of glioma." (PMID 27566584, 2016). "Based on the high affinity with IL-13Rα2, Interleukin-13 (IL-13) has been used as a ligand in glioma trials of immunotoxin therapy for GBM11." (PMID 26567528, 2015). "IL-13Rα2 is reported to be overexpressed on human tumors including glioma cell lines and with a high affinity for IL-13, which makes IL-13Rα2 an attractive target." (PMID 28344260, 2015). "In recent years, a few attempts have been reported to utilize IL-13 to enhance therapeutic effect of glioma." (PMID 28344260, 2015). "We do not, however, find any evidence for induction of IL13Rα2 through TNF/IL-4 or TNF/IL-13 cytokine regimens on glioma cell lines, either established (T98 or U251T) and/or low-passage primary lines (PBT003-4, PBT008, PBT017-4)." (PMID 24787244, 2014). "Expanded ex vivo, IL13(E13Y)-zetakine+ CTL retain MHC-independent IL13Rα2-specific anti-glioma cytolytic activity, maintain CAR-regulated Tc1 cytokine secretion and proliferation, and mediate regression of established human glioblastoma xenografts in vivo." (PMID 24787244, 2014). "U251 glioma cells expressing firefly luciferase (U251 ffl+) were co-cultured with increasing numbers of glioma-specific primary IL-13 zetakine CTLs that had migrated out of the fibrin matrix." (PMID 22496835, 2012). "IL-13-PE is reported to be more active against glioma cell lines than IL-4-targeted toxins in vitro." (PMID 22530127, 2012). "Our data indicated that IL-13 zetakine CTLs that had moved out of the fibrin matrix killed U251 glioma cells in a time and dose dependent fashion." (PMID 22496835, 2012). "A chimeric fusion protein composed of human IL-13 and mutated forms of Pseudomonas aeruginosa exotoxin A (PE38QQR) has been developed and shown to affect the specific cytotoxicity of glioma cell lines." (PMID 22530127, 2012). "The efficacy of protein DTAT13 that was synthesized to target uPAR on the neovasculature and uPAR- and interleukin-13-expressing glioblastoma cells has been demonstrated on glioma growth in vitro and in vivo." (PMID 20414463, 2010). "A fusion protein consisting of interleukin 13 (IL-13) and a mutated form of Pseudomonas exotoxin (IL-13-PE) has also been shown to induce potent and specific cytotoxicity in glioma cells that overexpresses the receptor for IL-13, IL13 receptor-α2 (IL13-Rα2)." (PMID 20942909, 2010).
glioma (continued). "Similarly, IL-13 muteins have been engineered into CARs for selective targeting of IL13Rα2-expressing gliomas, while natural receptor ectodomains such as NKp30 or NKp44 have been incorporated to leverage endogenous NK recognition mechanisms." (PMID 40941014, 2025). "Interestingly, IL-13 expression was significantly downregulated in patient glioma samples compared to the controls." (PMID 41034696, 2025). "In the tumor microenvironment, ZFP36 might reduce the growth and invasion of glioma cells by targeting IL-13 mRNA to inhibit the role of PI3K/Akt/mTOR pathways." (PMID 35800363, 2022). "The same study, however, also speculated that Th2 cytokines—such as interleukin (IL)-4 and IL-13—may hold protective roles against glioma via humoral immunity, including antibody production by stimulated B- cells." (PMID 34503270, 2021). "Strikingly, a single intracranial injection of IL13-zetakine CAR T cells into mice with orthotopic glioma xenografts led to a robust decrease in tumor burden and increased median overall survival from 35 to 40 days in control mice to 88 days in IL13-zetakine CAR T cell-treated mice." (PMID 34298615, 2021). "However, in glioma, IL13Rα2 binds to IL-13 with higher affinity, allowing for sequestration of IL-13 away from IL13Rα1." (PMID 33176788, 2020). "IL-13-related pathway has been already targeted while developing drug for gliomas." (PMID 30718742, 2019). "Our study demonstrated that the glioma cell lines produced only minute quantities of IL-13." (PMID 30572904, 2018). "We determined the total amount of IL-13 secreted by glioma cell lines." (PMID 30572904, 2018). "However, the glioma-initiating cells derived from IL13Rα2+ tumors express IL13αR2 at levels similar to differentiated cells and were similarly sensitive to in vitro IL13 zetakine therapy." (PMID 25247196, 2014). "The potential for targeting IL13Rα2-expressing GBMs has been demonstrated by early clinical experience at City of Hope in two phase I clinical trials with intracranial administration of first-generation IL13 zetakine T cell clones in patients with high-grade gliomas." (PMID 25247196, 2014). "However, an IL-13 receptor is expressed on some glioma cells and IL-13 has been shown to be an autocrine growth factor for both Reed-Sternberg cells in Hodgkin’s disease and pancreatic cancer." (PMID 23433400, 2013). "The potential contribution of the glioma cells to the increased IL-13 is under investigation." (PMID 23433400, 2013). "GBM etiology remains unclear, but IL-13 has been shown to be over expressed in a majority of glioma cell lines and GBM tumor tissues." (PMID 23663500, 2013). "Overexpression of IL-13 receptors has been reported in human gliomas, and conjugation of IL-13 to doxorubicin-loaded liposomes allowed a 5-fold reduction in tumor volume and extended survival of intracranial glioma tumor-bearing mice over untargeted doxorubicin-loaded liposomes." (PMID 23533772, 2013). "Hence further characterisation of the role and expression of IL-13 in gliomas is much needed." (PMID 41034696, 2025). "In addition, in vivo results showed that IL13‐bound Dp44mT‐NPs significantly inhibited glioma tumor growth and did not cause significant weight loss or renal/hepatic toxicity in mice." (PMID 38708806, 2024). "In addition to glioma, IL13Rα2 is expressed in a variety of malignancies that could be treated by systemic administration of IL13-CAR T cell therapy." (PMID 35939683, 2022). "Therefore, it is likely that IL-13 secreted by other cells in the systemic circulation may be involved in initiating signaling through AP-1 pathway in glioma tumors." (PMID 30572904, 2018). "Besides, previously results showed that IL4, IL4R and IL13 genes may play an important role in glioma survival." (PMID 23663500, 2013).
glioma (continued). "But in glioma tissues, there is obviously predominant expression of Th2 type cytokines, it may result tumor cells escape from immune response, so the abnormal secretion of IL-4, IL-10 and IL-13 may play an important role in the occurring and developing of human glioma." (PMID 23663500, 2013). "We found that the macro index performed better in predicting macrophages induced by IL13, IL4, and HDL, with similar efficiency between glioma groups." (PMID 36159811, 2022). "Glioma cells express multiple immune-suppressive cytokines such as transforming growth factor-beta (TGF-β), IL-10, IL-4, IL-6, and IL-13, all of which interfere directly or indirectly with anti-glioma immune response." (PMID 34084145, 2021). "The co-culture utilizes freshly-isolated bone marrow combined culture in 50% conditioned media from a 24-hour culture of the mouse glioma cell line GL261 and supplemented with GM-CSF and IL-13 to generate M-MDSCs and G-MDSCs over a 3-day period." (PMID 32625208, 2020). "These engineered IL13-zetakine+ T cells exhibit potent MHC-independent, IL13Rα2-specific cytolytic activity against both stem-like and differentiated glioma cells, and induce regression of established glioma xenografts in vivo." (PMID 24204956, 2013). "Our group has developed a platform to target high-grade gliomas based on IL13Rα2 expression by genetically modifying T cells to express an IL13Rα2-specific chimeric antigen receptor (CAR), IL13-zetakine." (PMID 24204956, 2013). "Intracavitary (resection-cavity) infusions of first-generation IL13(E13Y)-zetakine CAR T cells were well tolerated in 3 patients, producing transient anti-glioma activity in 2/3, with reduced IL-13Rα2 expression and new tumor necrosis on MRI (no grade ≥3 toxicity)." (PMID 41218126, 2025). "An investigation into glioma patients reported a positive correlation between serum soluble α-Klotho (sαKlotho) levels and IL-6 (p = 0.0347), along with other biomarkers such as VEGF, fractalkine, IFN-γ, GDNF, IL-4, and IL-13." (PMID 40426990, 2025). "Glioma cell have been illuminated to gang up on M2 macrophages which could be induced by IL4 and IL13 to invade the immune surveillance, especially in GBMs." (PMID 36434176, 2023). "Recently, we have reported that in the glioma microenvironment, levels of IL4, IL13, IL10, and TGFβ are increased by the IFNG response, which constitute a regulatory network of inflammatory responses and ultimately drives macrophages toward M2-type polarization." (PMID 35492352, 2022). "In the present study, we demonstrate for the first time that IL-13 can signal in situ in glioma samples rather than only in immortalized GBM cell lines." (PMID 30572904, 2018). "Similar to in vitro results, we demonstrated that IL-13Rα2 are overexpressed in glioma surgical specimens in situ and AP-1 transcription factors are constitutively activated without exogenous administration of IL-13." (PMID 30572904, 2018). "Neither mRNA nor proteins of the AP-1 transcription factors were upregulated after IL-13 treatment of IL-13Rα2 negative T98G glioma cell line." (PMID 30572904, 2018). "We have demonstrated up-regulation of two AP-1 transcription factors (c-Jun and Fra-1) at mRNA and protein levels upon treatment with IL-13 in IL-13Rα2 positive but not in IL-13Rα2 negative glioma cell lines." (PMID 30572904, 2018). "Previous studies (not shown) determined that human IL-13 (huIL-13) conjugated toxins did not result in efficient targeted killing of canine glioma cell lines in vitro." (PMID 24147065, 2013). "In the present study, we demonstrate that IL-13/IL-13Rα2 axis is important in mediating signal transduction by upregulating the AP-1 transcription factors in IL-13Rα2 positive, but not in IL-13Rα2 negative glioma cell lines." (PMID 30572904, 2018). "Despite these studies, it is not known whether IL-13 can signal through IL-13Rα2 in human glioma tumors in situ and whether it utilizes AP-1 pathway." (PMID 30572904, 2018).
glioma (continued). "Instead we demonstrate by immunoprecipitation experiments and mass spectrometry that the antigen recognized by the B-D13 antibody following cytokine stimulation is VCAM-1, and that VCAM-1, but not IL13Rα2, is induced on glioma cells by TNF alone or in combination with IL-13 or IL-4." (PMID 24787244, 2014). "These IL13-zetakine CAR T cells were specifically and potently activated in the presence of IL13Rα2-expressing glioma cells, whereas no appreciable effect was seen in the absence of IL13Rα2 expression." (PMID 34298615, 2021). "IL-13 itself has been reported to inhibit the anti-tumour response by downregulating CD8+ T cell immunosurveillance, although this study was not specific to gliomas." (PMID 41034696, 2025).
Pruritus (63 papers, 2016 to 2026). Pruritus is an itch or a sensation that makes a person want to scratch. "Among the implicated cytokines, IL-13 and IL-31 have been shown to promote the elongation and branching of sensory nerve fibers, thereby intensifying pruritus." (PMID 40364058, 2025). "Clinically, elevated IL-4, IL-13, and IL-31 are implicated in the pruritus seen in MF, with IL-31 levels correlating with both disease progression and symptom severity." (PMID 40864740, 2025). "Our study focused on investigating ex vivo skin biopsies in AD (n = 17), CNPG (n = 14) and healthy controls (HC; n = 10), examining the gene expression landscape of interleukins linked with pruritus (IL-13, IL-4, IL-31) and their corresponding receptors." (PMID 39126011, 2024). "IL-13 is considered a major mediator involved in the inflammation, epidermal barrier dysfunction, and pruritus associated with AD." (PMID 38590314, 2024). "IL-4, IL-13, and IL-31 are implicated in pruritus, offering therapeutic targets with dupilumab, tralokinumab, lebrikizumab, and nemolizumab." (PMID 38398754, 2024). "IL-13 plays a direct role in BP-associated pruritus by stimulating peripheral nerve fibers." (PMID 40507326, 2025). "AD is characterized by increased sensitization to IgE and increased immunological activities of Th2, leading to the production of interleukin (IL)-4, IL-13, IL-5, IL-31, and IL-10 and causing intense pruritus, xerotic skin, erythema, edema, erosion, and lichenification." (PMID 34253801, 2021). "In response to associated pruritus, there is prominent scratching behavior that leads to basophil-dependent IL-4 upregulation, but may lead to increased expression of the IL-13-decoy receptor IL-13RA2 and interruption of the IL-4/IL-13 signaling cascade as well." (PMID 39126011, 2024). "Th2 cytokines, such as interleukin-4 (IL-4) and interleukin-13 (IL-13), play a major role in orchestrating the inflammatory cascade, contributing to the hallmark features of AD both in the acute and chronic phases, including pruritus and eczematous skin lesions." (PMID 37892713, 2023). "IL-4 and IL-13 play key roles in the development of AD symptoms, namely, decreased integrity and barrier function of the skin and level of peptides associated with antibiotics, which further cause skin barrier abnormalities such as pruritus, xerosis, blister, pigmentation, and lichenification." (PMID 34253801, 2021). "Several cytokines, including TSLP, IL-13, IL-31, and IL-4, are involved in pruritus, one of the most prominent features of AD." (PMID 40429704, 2025). "When recruited eosinophils produce IL-4 and IL-13, more basophils are activated to produce IL-31, thereby forming a positive feedback loop that promotes BP-related pruritus." (PMID 40607386, 2025). "Th2 cytokines such as interleukin (IL)-4, IL-13, and IL-31 promote inflammation and pruritus, whereas regulatory cytokines including transforming growth factor-β1 (TGF-β1) help preserve immune homeostasis." (PMID 41227548, 2025). "This selective inhibition preserves upstream immune priming but blocks IL-13-driven peripheral effector functions, such as pruritus, tissue remodeling, and barrier impairment." (PMID 40725651, 2025). "In human AD, IL-4 and IL-13 promote IgE synthesis and barrier dysfunction, IL-31 induces pruritus via neuronal activation, and TGF-β1 mediates regulatory control." (PMID 41227548, 2025). "These pathways include cytokines, such as IL-4, IL-13, IL-31, and TSLP, and chemokines, such as CCL1, CCL13, and CCL17, which have been implicated in barrier disruption, pruritus, and immune cell recruitment in AD." (PMID 41583462, 2025). "Like AD, Th2-driven inflammation plays a major role in PN pathogenesis, with elevated levels of IL-4, IL-13, and IL-31 activating peripheral nerves via transient receptor potential channels, thereby eliciting pruritus." (PMID 40364058, 2025).